LZTS1 (leucine zipper tumor suppressor 1)
Diseases named in the same sentence as LZTS1 in open-access papers (continued):
Sharing a sentence is not in itself a finding about the gene and the disease.
tumor (continued). "For instance, FEZ1 (also known as LZTS1) is a tumor suppressor gene located at 8p22, a region frequently deleted in human tumors." (PMID 29435136, 2018). "Immunohistochemical evaluation of 67 cSCC tumor tissues demonstrated that miR-135b expression inversely correlated with LZTS1 staining intensity and the tumor grade." (PMID 25938461, 2015). "In this study we tested the expression of miR-135b and LZTS1 in cSCC tumor tissues obtained from IC and OTR patients and cSCC cell lines." (PMID 25938461, 2015). "We also demonstrated that overexpression of endogenous miR-135b in all three cSCC cell lines using specific miR-135b mimic further downregulated the mRNA LZTS1 expression and increased tumor cell motility and invasion." (PMID 25938461, 2015). "We focused on cell cycle regulation and one of the genes, LZTS1, which has previously been described as a tumor suppressor and a cell cycle regulator, and investigated its functional role in the mechanisms of Docetaxel resistance." (PMID 24525428, 2014). "LZTS1 deficient mice develop cancers with diverse histogenetic backgrounds, suggesting that LZTS1 acts as a major tumor suppressor gene in multiple cell types." (PMID 24448468, 2014). "Correspondingly, the LZTS1 mRNA expression was reduced in the tumor samples, suggesting a strong influence of 5hmC on mRNA expression." (PMID 25248841, 2014). "The Leucine Zipper Tumor Suppressor 1 (LZTS1) is a tumor suppressor gene, located at chromosome 8p22, which is frequently altered in human cancer." (PMID 24448468, 2014). "For example, FEZ1/LZTS1 (Leucine zipper putative tumour suppressor 1) is a tumour suppressor gene important for cell cycle control." (PMID 22412920, 2012). "Experimental studies using different cancer derived cell lines from human bladder, breast and prostate tumor, showed that reintroduction of LZTS1 results in inhibition of tumor cell growth in vitro and/or tumorigenicity in vivo." (PMID 17718912, 2007). "Together, these results challenge the notion that LZTS1 functions as a tumour suppressor in cancer." (PMID 39023696, 2024). "Furthermore, we found that the expression of LZTS1 was significantly increased in CRC tumour samples based on two individual GEO datasets." (PMID 39023696, 2024). "LZTS1 exhibited a lower protein level in tumor tissues than normal tissues." (PMID 37237274, 2023). "Lzts1 codes for a tumor suppressor that may stabilize the active CDC2-cyclin B1 complex and thereby contributes to the regulation of the cell cycle and the prevention of uncontrolled cell proliferation." (PMID 35267932, 2022). "Since LZTS1 has been reported as a biomarker of poor clinical outcome in other tumor types, we hypothesized that miR-135b could influence the metastatic invasiveness of cSCC by modulating LZTS1expression." (PMID 25938461, 2015). "Similarly for LZTS1, with adjacent probes included, methylation was highly specific to basal-like tumours with AUC of 0.95 and 0.86 in the training and test cohorts, respectively." (PMID 25960784, 2015). "The resulting increase in LZTS1 levels suppressed cSCC cell migration and invasion without affecting cell proliferation, demonstrating that miR-135b is an oncomir that functions via downregulation of the LZTS1 tumor-suppressor gene." (PMID 25938461, 2015). "We detected reduced LZTS1 staining intensity in the tumor samples from OTRs." (PMID 25938461, 2015). "Using multiple gain-of-function and loss-of-function assays, we describe for the first time that LZTS1 is indeed a target gene of miR-135b in cSCC and mirR-135b expression inversely correlates with staining intensity of LZTS1and tumor grade in cSCC tumor samples." (PMID 25938461, 2015). "FEZ1/LZTS1 (leucine zipper tumor suppressor 1) is a putative tumor suppressor gene located at 8p22." (PMID 15357873, 2004). "Furthermore, the tumour samples at an advanced stages showed the lowest methylation level of LZTS1." (PMID 39023696, 2024).
tumor (continued). "Thus data from our study suggest that miR-135b might similarly influence cSCC progression through modulation of tumor suppressors, such as LZTS1." (PMID 25938461, 2015). "This microRNA promotes tumor growth by targeting LATS2 (Large tumor suppressor kinase 2) and enhances invasiveness by inhibiting LZTS1 (Leucine zipper tumor suppressor 1)." (PMID 40399946, 2025). "Immunofluorescence analysis also showed that both LZTS1 and pAKT were consistently high expressed in CRC tumour samples." (PMID 39023696, 2024). "In keeping with the expression pattern of LZTS1 in COAD and READ, the methylation level of the LZTS1 promoter was significantly lower in tumour samples of COAD or READ with different tumour grades or N stage, compared to normal tissues." (PMID 39023696, 2024). "We found that most genes with hazard ratio > 1 (GPRASP1, APLP1, ALPK3, SPTBN5, PCDHB14, LZTS3 and RGL2) have a higher expression in tumor tissues than normal tissues except LINGO1 and LZTS1." (PMID 37237274, 2023). "The leucine zipper putative tumor suppressor 1 (LZTS1, previously named FEZ1) gene was identified as a tumor suppressor gene at 8p22." (PMID 24448468, 2014). "The 8p22 region identified in our GBCs spans the FEZ1/LZTS1 gene, a candidate TSG, whose expression is altered in multiple human tumours." (PMID 12177780, 2002). "We found that the expression of LZTS1 is higher in tumour samples compared to paired normal tissue in CRC cancer and its different clinical subtypes, which is, at least in part, due to the low methylation status of LZTS1 promoter in CRC tumour samples." (PMID 39023696, 2024). "Here, our results show that the expression of LZTS1 is higher in CRC tumour samples compared to their paired normal tissue in both public datasets and our cohort." (PMID 39023696, 2024). "Consistently, we found that the expression of LZTS1 positively correlated with the expression PIK3CD, N‐cadherin in CRC tumour samples, while the expression of LZTS1 negatively correlated with the expression of E‐cadherin and PTEN in CRC tumour samples." (PMID 39023696, 2024). "LZTS1 staining intensity was also diminished in the 42 (8 OTRs and 34 IC) paraffin-embedded tumor samples (71.02 ± 36.5) when compared to non-lesional skin (227.5 ± 8.3; p<0.001)." (PMID 25938461, 2015). "Restoration of LZTS1 expression in LZTS1-negative cancer cells resulted in the suppression of tumorigenicity, reduced tumor cell growth, and arrested cells at the late S-G2/M phase of the cell cycle." (PMID 25813822, 2015). "Furthermore, in the CRC patients without metastasis, LZTS1 expression was significantly upregulated in the tumour tissues compared to the normal tissues." (PMID 39023696, 2024). "LZTS1 is transcriptionally activated by HOXB8 and might, as other genes from the same cluster, provide additional mechanisms by which HOXB8 reverses MEK1ca-induced neoplasia." (PMID 34445617, 2021). "However, the role of LZTS1 in cSCC progression and the clinical implication between miR-135b expression, LZTS1 expression and histological tumor grade has not yet been tested." (PMID 25938461, 2015). "Therefore, we suggest that, in absence of LZTS1 expression, tumor cells are able to bypass the checkpoint, are not arrested in mitosis and do not show features of mitotic catastrophe, suggesting that targeting the checkpoint might provide a mean to induce apoptosis in resistant cells." (PMID 24525428, 2014).
cancer (21 papers, 2007 to 2024). A tumor composed of atypical neoplastic, often pleomorphic cells that invade other tissues. "In human cancer cell lines, repression of LZTS1 causes aggressive phenotypes by regulating the PI3K‐AKT pathway." (PMID 39023696, 2024). "Western blot and RT-PCR analyses in different cancer derived cell lines showed similar result, arguing that loss or reduction of LZTS1 is a frequent event in cancer development and progression." (PMID 17718912, 2007). "Overall, ~60% of different primary tumors showed loss or reduction of Lzts1 protein expression in cancer cells." (PMID 17718912, 2007). "Furthermore, deletion of LZTS1 in mouse embryos predisposes mice to cancer development by accelerating mitotic progression." (PMID 39023696, 2024). "To date, studies have detected LZTS1 mutations in different cancers, but they are uncommon." (PMID 25813822, 2015). "Indeed, LZTS1 knockout results in accelerated mitotic progression, improper chromosome segregation and predisposes mice to cancer." (PMID 24525428, 2014). "Additionally, there were theories suggest that hypermethylation of the promoter region of LZTS1 could induce the deficient of LZTS1 in cancer cells." (PMID 33637680, 2021). "In addition LZTS1 is also mutated and/or deleted in several cancer types." (PMID 17718912, 2007). "In this study, we showed that the expression of LZTS1 was higher in CRC tissues as well as multiple other cancer types compared to normal tissues, and its overexpression was correlated with poor survival in CRC." (PMID 39023696, 2024). "Our analysis showed that the expression of LZTS1 was significantly upregulated in eight types of cancer including COAD and READ." (PMID 39023696, 2024). "Leucine zipper putative tumor suppressor 1 (LZTS1) was reported to suppress cancer cell growth and regulate cell cycle." (PMID 35126454, 2021). "Theories suggested that hypermethylation of the promoter regions of LZTS1 was responsible for LZTS1 abnormal expression in multiple malignant tumors." (PMID 33637680, 2021). "Though the role and mechanism involved of LZTS1 protein was well studied in various types of malignant tumors such as stomach, lung, bladder, ovary, and kidney, the functional role of LZTS1 in kidney stone disease is unreported." (PMID 32867742, 2020). "LZTS3 is a putative tumour suppressor family member, expressed in human oviduct, highly similar to LZTS1 that inhibits cancer cell growth through the regulation of mitosis and it is considered as a roadblock to reprogramming." (PMID 27448656, 2016). "In contrast, miR-135b overexpression by synthetic miR-135b mimic induced further down-regulation of LZTS1 mRNA in vitro and increased cancer cell motility and invasiveness." (PMID 25938461, 2015). "Ubiquitous expression of LZTS1 protein has been detected in normal tissues; however, it is reduced or lost in different cancer tissues and cells, including gastric, lung, bladder, oral, and kidney cancers." (PMID 25813822, 2015). "By the functional point of view, Lzts1 inhibits cancer cell growth through the regulation of the mitotic process." (PMID 24448468, 2014). "The analysis showed a significant LZTS1 mRNA downregulation in invasive ductal (fold change -1.901; p=1.47E-9) and lobular (fold change -1.581; p=1.21E-4) carcinoma samples in comparison to normal breast." (PMID 24448468, 2014). "To date, several new candidate cancer-susceptible genes have been cloned to 8p22, such as deleted in breast cancer 2 (DBC2), leucine zipper tumor suppressor 1 (LZTS1), deleted in liver cancer 1 (DLC1), and mitochondrial tumor suppressor 1 (MTUS1)." (PMID 22028972, 2012). "In these studies we pointed out that LZTS1 inhibits cancer cell growth through the regulation of mitosis, interacting with CDK1, an important factor for G2/M transition of cell cycle." (PMID 17718912, 2007).
cancer (continued). "Recently we identified a new player: FEZ1/LZTS1 that contributes to the fine-tuning of the molecular events that determine progression through mitosis, and here will review its role in cancer development and in M phase regulation." (PMID 17718912, 2007). "Moreover, several studies reported that expression of LZTS1 is higher in cancer tissues, compared to matched control samples, indicating the oncogenic function of LZTS1 in carcinogenesis." (PMID 39023696, 2024). "Consequently, a comprehensive understanding of the precise mechanisms governing LZTS1's impact on the PI3K‐AKT pathway holds potential significance for tailoring therapeutic strategies in cancer treatment." (PMID 39023696, 2024). "LZTS1 has been found dysregulated in many cancers, especially in CRC." (PMID 33637680, 2021). "Indeed, our previous study showed that re-expression of LZTS1 in the highly metastatic MDA-MB-231 cell line resulted in an inhibition of cancer cell proliferation, migration and invasion, and suppression of epithelial-to-mesenchymal transition." (PMID 25813822, 2015). "Hypermethylation of LZTS1 CpG islands could be responsible for the reduced expression of LZTS1 in cancer cells." (PMID 25813822, 2015). "Being Lzts1 frequently down-regulated in many human tumors further investigations are needed in order to better understand its functions, eventually uncovering new opportunities for approaching cancer and other proliferation-related diseases." (PMID 17718912, 2007). "A total of 8 cancer genes with an OncoScore above the 90th percentile was identified (TNFRSF10B, TNFRSF10C, TNFRSF10A, TNFRSF10D, LZTS1, NKX3-1, BNIP3L and RHOBTB2; OncoScore range: 71.4–86.3)." (PMID 28387367, 2017). "MiR-135b expression enhances cancer cell invasive and migratory abilities in vitro and promotes cancer metastasis in vivo by targeting multiple key components on the Hippo pathway, including LATS2, BTRCP and NDR2, as well as LZTS1." (PMID 28915579, 2017). "Out of those four genes, three (RHOC, LZTS1, ARHGDIG) are known cancer genes." (PMID 34762640, 2021). "Immunohistochemical studies of primary tumors indicated that Lzts1 protein expression in cancer cells is absent or markedly reduced in many different cancers compared with non-cancerous tissue." (PMID 17718912, 2007).
adenocarcinoma (1 paper, 2024). A common cancer characterized by the presence of malignant glandular cells. "As for adenocarcinoma and mucus adenocarcinoma, both COAD and READ showed decreased LZTS1 expression compared to normal tissue." (PMID 39023696, 2024). "As for adenocarcinoma and mucus adenocarcinoma, both COAD and READ showed enhanced LZTS1 expression compared to normal tissue, along with increased trend of LZTS1 in mucus adenocarcinoma." (PMID 39023696, 2024).
neurodevelopmental disorder (1 paper, 2019). A behavioral and cognitive disorder with onset during the developmental period that involves impaired or aberrant development of intellectual, motor, or social functions. "These psychiatric and neurodevelopmental disorders have been explained by impaired synaptic transmission from glutamatergic neurons, as suggested by previous studies in Lzts1 KO mice." (PMID 31239441, 2019).
psychiatric disorder (1 paper, 2019). A disorder characterized by behavioral and/or psychological abnormalities, often accompanied by physical symptoms. "Moreover, the disorganized production of oRGs induced by altered Lzts1 function might be involved in psychiatric disorders." (PMID 31239441, 2019).
LZTS1 also shares sentences with these, for which no sentence is quoted: gastric cancer (2 papers); Breast (1); celiac disease (1); cervical cancer (1); Crohn disease (1); cutaneous squamous cell carcinoma (1); endometrial cancer (1); hepatocellular carcinoma (1); Intellectual disability (1); leukemia (1); liver cancer (1); lung adenoma (1); lymphoma (1); ovarian adenocarcinoma (1); ovarian tumours (1); rectal adenocarcinoma (1); rheumatoid arthritis (1); soft tissue sarcoma (1); uveal melanoma (1).